RAD51D (RAD51 paralog D)
Description:
Involved in the homologous recombination repair (HRR) pathway of double-stranded DNA breaks arising during DNA replication or induced by DNA-damaging agents. Bind to single-stranded DNA (ssDNA) and has DNA-dependent ATPase activity. Part of the RAD51 paralog protein complex BCDX2 which acts in the BRCA1-BRCA2-dependent HR pathway. Upon DNA damage, BCDX2 acts downstream of BRCA2 recruitment and upstream of RAD51 recruitment. BCDX2 binds predominantly to the intersection of the four duplex arms of the Holliday junction and to junction of replication forks. The BCDX2 complex was originally reported to bind single-stranded DNA, single-stranded gaps in duplex DNA and specifically to nicks in duplex DNA. Involved in telomere maintenance. The BCDX2 subcomplex XRCC2:RAD51D can stimulate Holliday junction resolution by BLM.
Synonyms: RAD51L3; R51H3; Trad; HsTRAD; BROVCA4
Tractability: Small molecule: a structure with a bound ligand is known. PROTAC: ubiquitination databases record sites on it.
Gene: Protein-coding gene on chromosome 17 (35,092,221 to 35,121,522, reverse strand). Ensembl gene ENSG00000185379.
Subcellular location: Nucleus; Cytoplasm, cytoskeleton, microtubule organizing center, centrosome; Chromosome, telomere
Pathways (Reactome):
DNA Repair: HDR through Homologous Recombination (HRR); Homologous DNA Pairing and Strand Exchange; Presynaptic phase of homologous DNA pairing and strand exchange; Resolution of D-loop Structures through Holliday Junction Intermediates; Resolution of D-loop Structures through Synthesis-Dependent Strand Annealing (SDSA)
Disease: Defective HDR through Homologous Recombination Repair (HRR) due to PALB2 loss of BRCA1 binding function; Defective HDR through Homologous Recombination Repair (HRR) due to PALB2 loss of BRCA2/RAD51/RAD51C binding function; Defective homologous recombination repair (HRR) due to BRCA1 loss of function; Impaired BRCA2 binding to PALB2
Gene Ontology:
Molecular function: ATP-dependent activity, acting on DNA; ATP-dependent DNA damage sensor activity; four-way junction DNA binding; gamma-tubulin binding; protein binding; single-stranded DNA binding; DNA binding; ATP binding
Biological process: DNA strand invasion; double-strand break repair via homologous recombination; supramolecular fiber organization; telomere maintenance; telomere maintenance via recombination; DNA repair; reciprocal meiotic recombination
Cellular component: centrosome; chromosome, telomeric region; Rad51B-Rad51C-Rad51D-XRCC2 complex; replication fork; microtubule organizing center; nucleoplasm; nucleus
Genetic constraint (gnomAD): Loss-of-function variants: 38 observed, 45.62 expected, observed/expected ratio (o/e) 0.83, 90% interval 0.64 to 1.09. The upper end of that interval is the gene's LOEUF score, 1.09, which puts it in group 4 of 6, group 1 being the genes least tolerant of losing a copy. Missense variants: 390 observed, 424.39 expected, observed/expected ratio (o/e) 0.92, 90% interval 0.85 to 1. Synonymous variants: 141 observed, 170.13 expected, observed/expected ratio (o/e) 0.83, 90% interval 0.72 to 0.95.
Gene-disease validity (ClinGen):
ClinGen rates the evidence that RAD51D causes each of these diseases.
RAD51D-related cancer predisposition (autosomal dominant): Definitive. Hereditary cancer predisposition due to variation(s) in the RAD51D gene.
Cancer hallmarks: genome instability and mutations (suppresses); proliferative signalling (promotes); cell replicative immortality (promotes); escaping programmed cell death (promotes)
Homologues: Orthologues: chimpanzee RAD51D (88% identical), guinea pig RAD51D (88% identical), pig RAD51D (85% identical), mouse Rad51d (83% identical), dog RAD51D (80% identical), tropical clawed frog rad51d (56% identical), zebrafish rad51d (55% identical), Caenorhabditis elegans rfs-1 (19% identical). Paralogues in human: RAD51B (26% identical), XRCC3 (24% identical), RAD51C (23% identical), DMC1 (21% identical), RAD51 (21% identical), XRCC2 (13% identical).
Diseases named in the same sentence as RAD51D in open-access papers:
RAD51D is named in the same sentence as 63 diseases in open-access papers, as found by Europe PMC text mining. Sharing a sentence is not in itself a finding about the gene and the disease. The quoted sentences say what the papers report.
ovarian carcinoma (143 papers, 2012 to 2026). A malignant neoplasm originating from the surface ovarian epithelium. "Similar to pathogenic RAD51C variants, RAD51D-associated ovarian cancer risk remains low at younger ages (cumulative risk to age 50: 0.8%) but rises markedly thereafter." (PMID 41528496, 2026). "RAD51D has been associated with an increased risk of ovarian cancer, with an estimated germline prevalence of approximately 1% in ovarian cancer patients." (PMID 40926019, 2026). "Truncating variants in BRCA1, BRCA2, BRIP1 and RAD51D represent high‐risk variants for breast or ovarian cancer." (PMID 39440754, 2025). "Background/Objectives: Germline pathogenic variants (GPVs) in PALB2, RAD51C, and RAD51D increase breast cancer (BC) and ovarian cancer (OC) risk." (PMID 40428378, 2025). "Our study identified 19/728 carriers (2.6%) of pathogenic HDR gene variants, including 15 truncating variants, of which 4 were in BRCA1 or BRCA2 (0.5%) and 4 were in BRIP1 or RAD51D, two other genes associated with high ovarian cancer risk." (PMID 39440754, 2025). "One subject with a rare fallopian tube cancer and family history of ovarian cancer had a frameshift mutation in RAD51D, which has been associated with cancer risk." (PMID 38996041, 2025). "Mutation frequencies of RAD51C and RAD51D for unselected ovarian cancer patients ranged from 0.2% to 1.1% and 0.35% to 1.1%, respectively." (PMID 39202057, 2024). "A meta-analysis of ~29,400 ovarian cancer patients revealed RAD51D to be one of the highest-risk genes related to ovarian cancers." (PMID 39202057, 2024). "For RAD51C and RAD51D PGVs carriers, it is estimated: (i) the absolute risk of BC is 10–40% and (ii) the absolute risk of epithelial ovarian cancer is 10–20%." (PMID 38672070, 2024). "In a large Chinese cohort of ovarian cancer patients, RAD51D GPVs were detected in 1.7% (13/781), and this variant was found in seven patients and accounted for 53.8% of all RAD51D pathogenic variants." (PMID 39202057, 2024). "Individuals who carry RAD51C or RAD51D mutations have a significantly higher risk of developing breast or ovarian cancers than the general population." (PMID 39202057, 2024). "The association of RAD51C and RAD51D GPVs with ovarian cancer susceptibility was first proposed in 2011." (PMID 39202057, 2024). "RAD51D’s loss-of-function mutation is an inclusion criterion for trials evaluating the effectiveness of Rucaparib in ovarian cancer or prostate cancer, Talazoparib in HER2-negative BC, and Niraparib in pancreatic cancer." (PMID 39202057, 2024). "In a study conducted on Chinese ovarian cancer patients, a correlation was observed between the RAD51D mutation and the HRD score determined by their in-house-developed HRD assay." (PMID 39202057, 2024). "c.270_271dupTA; p.(Lys91Ilefs*13) mutation carriers with high-grade ovarian cancer with metastasis also demonstrated a good response to PARPi for 15 months before the gain of secondary somatic RAD51D mutation." (PMID 39202057, 2024). "In terms of other PARP inhibitors, RAD51C and RAD51D mutations predicted response to treatment with rucaparib patients with relapsed ovarian cancer in a post hoc exploratory analysis of ARIEL2." (PMID 39695768, 2024). "Associations of RAD51C and RAD51D germline pathogenic variants (GPVs) with breast and ovarian cancer predisposition have been recently reported and are of interest." (PMID 39202057, 2024). "The estimated risk associated with RAD51C and RAD51D were odd ratios of 5.2 (95% CI, 1.1 to 24) and 12 (95% CI, 1.5–90), respectively, and confirmed their strong association with ovarian cancer." (PMID 39202057, 2024). "This study evaluated the prevalence of RAD51C and RAD51D genes in Chinese high-risk breast and/or ovarian cancer patients." (PMID 39202057, 2024). "RAD51C and RAD51D germline alterations have been associated with increased ovarian cancer risk, whereas their contribution to BC risk is less clear." (PMID 37347260, 2023).
ovarian carcinoma (continued). "The contribution of the RAD51C and RAD51D deleterious variants to ovarian cancer has been previously established by numerous studies, but their role in BC predisposition is now emerging." (PMID 37628581, 2023). "Germline PVs in the HR-related genes BRIP1, PALB2, RAD51C and RAD51D have an established role in increasing a patient's risk of ovarian cancer." (PMID 36805919, 2023). "An acquired mutation can reverse a loss-of-function change in RAD51D and can result in PARPi resistance in a hereditary ovarian cancer patient." (PMID 37833926, 2023). "Collectively, germline mutations in BRIP1, RAD51C, and RAD51D account for around 2% of ovarian cancer cases." (PMID 35805770, 2022). "RAD51D analysis should be implemented into the multi-gene testing for high-risk ovarian cancer patients." (PMID 36544182, 2022). "Clinicopathological characteristics, treatment modalities, and outcomes for ovarian cancer patients with RAD51D germline mutations should be studied in prospective manner and further independent studies are warranted to confirm this observation." (PMID 36544182, 2022). "In the current study, we investigated the clinical characteristics and survival of Chinese ovarian cancer patients with RAD51D germline mutations." (PMID 36544182, 2022). "We have investigated RAD51C and RAD51D, hereditary ovarian cancer risk genes, in French Canadians of Quebec, Canada." (PMID 35565380, 2022). "The age at ovarian cancer diagnosis is older for women with mutations in RAD51D, suggesting that it is safe to delay risk-reducing salpingo-oophorectomy (RRSO) until age 45–50 in RAD51D mutation carriers." (PMID 36544182, 2022). "In our large cohort of Chinese ovarian cancer patients, RAD51D c.270_271dup was the most frequency pathogenic variant, accounting for 53.8% of all RAD51D pathogenic variants." (PMID 36544182, 2022). "RAD51D germline mutations are more frequent in Chinese ovarian cancer patients than other population." (PMID 36544182, 2022). "Clinicopathological characteristics, treatment modalities, and outcomes were assessed for ovarian cancer patients with RAD51D germline mutations." (PMID 36544182, 2022). "In another study evaluating the contribution of RAD51 genes, small proportions of pathogenic mutations in RAD51C (14/3429, 0.41%) and RAD51D (12/3429, 0.35%) in invasive epithelial ovarian cancer were identified." (PMID 35608067, 2022). "The National Comprehensive Cancer Network (NCCN) guidelines for breast and ovarian cancer recommend that RRSO should be considered beginning at age 45 to 50 years in women carriers of germline variants in RAD51D." (PMID 36544182, 2022). "We aimed to describe the behavior among Chinese ovarian cancer patients with RAD51D germline mutations at our institution." (PMID 36544182, 2022). "A recent meta-analysis of approximately 23,000 ovarian cancers ranked RAD51D as a relatively high cancer risk gene." (PMID 36544182, 2022). "The data presented here for BRIP1, RAD51C, and RAD51D supports previous research demonstrating an increased risk of ovarian cancer for women with PVs in these genes." (PMID 33926482, 2021). "The penetrance of RAD51D for ovarian cancer is at moderate risk, which is almost consistent across ethnicities." (PMID 35008774, 2021). "Germline variants of RAD51D, most of which are truncated, were principally shown in ovarian cancer with an estimated six-fold increase in risk." (PMID 34838098, 2021). "RAD51D (RAD51 paralog D) is an intermediate cancer susceptibility gene for primary ovarian cancer, including fallopian tube and peritoneal carcinomas and breast cancer." (PMID 34838098, 2021). "The association between RAD51D pathogenic mutations and ovarian cancer has already been established, endorsing the causal role of the c.94_95delGT RAD51D mutation in the patient’s pathogenesis." (PMID 32756499, 2020).
ovarian carcinoma (continued). "Recently, several pieces of evidence showed that mutations in three genes involved in the homologous recombination DNA repair pathway, i.e., BRIP1, RAD51C, and RAD51D, are associated with a high risk of ovarian cancer." (PMID 32359370, 2020). "It is estimated that the frequency of RAD51C and RAD51D germline mutations in ovarian cancer patients is 3% and 5%, respectively." (PMID 33015624, 2020). "The meta-analysis provides evidence supporting the pathogenicity of BRIP1, RAD51C, and RAD51D mutations in relation to ovarian cancer." (PMID 32359370, 2020). "Mutations in BRIP1, RAD51C, or RAD51D are associated with an increased risk of developing ovarian cancer." (PMID 32733558, 2020). "The prevalence rate of BRIP1, RAD51C, or RAD51D pathogenic variants is about 1% in women with ovarian cancer." (PMID 32733558, 2020). "Based on the best available evidence, variants in BRCA1, BRCA2, BRIP1, RAD51C, RAD51D, and the mismatch repair genes confer ovarian cancer risks that warrant the consideration of risk-reducing surgery." (PMID 33086730, 2020). "Deficiency in the canonical RAD51 paralogs, such as RAD51C and RAD51D, are linked to familial breast and ovarian cancer predisposition." (PMID 31665741, 2019). "BARD1, PALB2, and RAD51B variants have been identified in breast cancer families, whereas truncating RAD51C and RAD51D variants are mainly found in families with ovarian cancer or breast and ovarian cancer." (PMID 30689231, 2019). "Nevertheless, other studies have indicated that mutations in RAD51C and RAD51D contribute to the risk of both breast and ovarian cancer, and that RAD50 is an intermediate-risk breast cancer susceptibility gene." (PMID 29566657, 2018). "Loveday and colleagues identified truncating RAD51D mutations in 8 of 911 familial breast-ovarian cancer pedigrees, demonstrating that RAD51D mutations confer a sixfold increased risk of ovarian cancer but cause only a small increase in breast cancer." (PMID 26075229, 2015). "Deleterious germline mutations in the RAD51C and RAD51D genes confer an increased risk of ovarian cancer whereas common polymorphisms in the RAD51B gene are associated with male and female breast cancer." (PMID 25918678, 2015). "While germline mutations in RAD51C and RAD51D are associated with high ovarian cancer risk and RAD51B polymorphisms with breast cancer, the contribution of RAD51, XRCC3, and XRCC2 is more unclear." (PMID 25918678, 2015). "Loss-of-function mutations in RAD51D gene seem to predispose to ovarian cancer, while there is doubtable association to breast cancer susceptibility." (PMID 23586058, 2013). "The ovarian cancer relative risk for carriers of RAD51D mutations is estimated to be 6.3, while the relative risk for breast cancer is not statistically significant." (PMID 23586058, 2013). "Mutations in RAD51D have been associated with an increased risk of hereditary ovarian cancer and although they have been observed in the context of breast and ovarian cancer families, the association with breast cancer is unclear." (PMID 23372765, 2013). "Our data provide additional evidence that RAD51D mutations are enriched among ovarian cancer patients, but are extremely rare among familial breast cancer patients." (PMID 23372765, 2013). "The aim of this current study was to validate the reported association of RAD51D with ovarian cancer and assess for an association with breast cancer." (PMID 23372765, 2013). "Testing of RAD51D in women with ovarian carcinoma, who have at least one relative with ovarian carcinoma, is likely to identify mutations in 1–5% of cases." (PMID 22415235, 2012). "In 175 families selected, having one or more ovarian cancer cases, we identified one deleterious truncating p.Arg186* mutation in RAD51D, previously identified in two unrelated families from the UK." (PMID 22415235, 2012).
ovarian carcinoma (continued). "We studied ovarian and breast cancer families having at least one woman affected by ovarian carcinoma, to assess the importance of RAD51D mutations in such families." (PMID 22415235, 2012). "RAD51D is an established susceptibility gene in ovarian cancer, involved in DNA repair." (PMID 39031169, 2024). "Apart from BRCA1/2, recent studies have revealed that the somatic reversion mutations of the core HR genes, RAD51C and RAD51D, might be mechanisms of acquired resistance to the PARPis, rucaparib, in ovarian cancers." (PMID 37833926, 2023). "Moreover, a recent meta-analysis provided evidence supporting the pathogenicity of BRIP1, RAD51C, and RAD51D mutations in relation to ovarian cancer, cumulatively contributing to ~2% of ovarian cancer cases." (PMID 37444530, 2023). "To date, germline RAD51D mutations have only been associated with increased risk of ovarian cancer and ATM germline mutations have primarily been shown to increased risk of breast cancer as well as case familial cases of ovarian, prostate, and pancreatic cancers." (PMID 37576901, 2023). "We found that RAD51D germline mutations are more frequent in Chinese ovarian cancer patients and these patients may derive benefit from PARPis treatment." (PMID 36544182, 2022). "RAD51D mutation testing may have clinical utility in individuals with ovarian cancer and their families." (PMID 36544182, 2022). "Our findings support the role of inherited variants in RAD51C and RAD51D in ovarian cancer." (PMID 35565380, 2022). "In addition, BRCA1/2, ATM, BRIP1, PALB2, RAD51C, and RAD51D gene mutations are reported to be associated with high risk of ovarian cancers, and from the results of tumor tissue, it is easy to further determine their genetic status." (PMID 35186721, 2022). "Interestingly, there is overlap in site and cisplatin sensitivity of peritoneal mesothelioma and ovarian cancer, a type of cancer for which 18% to 24% of patients will carry a germline mutation in the RAD51D gene." (PMID 34948918, 2021). "RAD51D loss-of-function variants increase lifetime risk of breast and ovarian cancer." (PMID 34200360, 2021). "RAD51D loss-of-function variants confer risk of breast and/or ovarian cancer." (PMID 34200360, 2021). "In a population-based cohort and a screening trial of individuals at high risk of ovarian cancer, both RAD51C and RAD51D were shown to be moderately susceptible to ovarian cancer, suggesting the usefulness of these genes alongside BRCA1/2 for the prediction of susceptibility to ovarian cancer." (PMID 34838098, 2021). "Additionally, pathogenic alterations in PALB2, ATM, CHEK2, and NBN are correlated with an increased risk for breast cancer and/or other cancers, whereas other genes such as BRIP1, RAD51C, and RAD51D are associated with an increased ovarian cancer risk." (PMID 32733558, 2020). "To more precisely estimate the ovarian cancer risk attributed to BRIP1, RAD51C, and RAD51D mutations, we performed a meta-analysis based on a comparison of a total of ~ 29,400 ovarian cancer patients from 63 studies and a total of ~ 116,000 controls from the gnomAD database." (PMID 32359370, 2020). "The level of ovarian cancer risk conferred by these mutations is relatively high, indicating that after BRCA1 and BRCA2, the BRIP1, RAD51C, and RAD51D genes are the most important ovarian cancer risk genes, cumulatively contributing to ~ 2% of ovarian cancer cases." (PMID 32359370, 2020). "Germline mutations in both RAD51C and RAD51D were identified in families with ovarian cancer." (PMID 30672100, 2019). "Mutations in RAD51D are associated with an increased risk of ovarian cancer and a Finnish founder mutation c.576+1G>A in the gene was significantly more frequent among breast cancer patients with a family history of breast and ovarian cancer (2.9%) than among population controls (0.1%)." (PMID 28874143, 2017).